APOA1 (apolipoprotein A1)
Diseases named in the same sentence as APOA1 in open-access papers (continued):
Sharing a sentence is not in itself a finding about the gene and the disease.
cancer (continued). "Therefore, our study using a single‐center prospective PCI registry database aimed to clarify the possible associations of serum levels of HDL‐C and ApoA1 with subsequent cancer mortality in this population." (PMID 35796324, 2022). "Therefore, further investigations with larger sample sizes are needed to assess the associations of ApoA1 with specific types of cancer." (PMID 35796324, 2022). "Indeed, a number of clinical studies have discovered associations between the reduced levels of serum ApoA1 and increased risk of many types of cancer in general population." (PMID 35796324, 2022). "Finally, because of the relatively small number of total participants and endpoint incidence, evaluating the contribution of ApoA1 to the risk of specific cancer types was underpowered." (PMID 35796324, 2022). "Low HDL cholesterol and apolipoprotein A1 were associated with increased risk of several cancers." (PMID 32998735, 2020). "As a major protein constituent of high density lipoprotein, Apolipoprotein A1 (ApoA-1) might be associated with cancer progression." (PMID 27683106, 2016). "Thus, the normal expression of APOA1 causes cancer cell apoptosis." (PMID 38067270, 2023). "For example, the ApoA1 mimetic peptide, L-5F was reported to prevent angiogenesis, suggesting that it may have therapeutic potential against angiogenesis associated diseases such as cancer." (PMID 32411725, 2020). "The U‐shaped association between cancer mortality and HDL‐C, or its components ApoA1, has been explored by several studies in recent years." (PMID 39912426, 2025). "A comprehensive cancer detection tool employing established biomarkers (ApoA1, CA125, CA19-9, CEA, ApoA2, and TTR) has demonstrated promise in predicting multiple cancers at a reasonable cost." (PMID 38540782, 2024). "Data from epidemiological and animal research point to a potential involvement of APOA1 in different cancer types." (PMID 37375802, 2023). "In the present study involving patients with established atherosclerotic coronary artery disease, the effect of preprocedural ApoA1 level on total cancer mortality was significant compared to HDL‐C level." (PMID 35796324, 2022). "Clinical investigations elaborated on the association of plasma apolipoprotein A1 (APOA1)/HDL levels and the risk of developing cancer, whereby the large majority of the studies reported an inverse association." (PMID 35577388, 2022). "The present study involving 3835 patients who underwent PCI demonstrated that the incidence of cancer mortality, GI cancer mortality in particular, was significantly higher in patients with lower ApoA1 at PCI procedure." (PMID 35796324, 2022). "ApoA1 and ApoE are elevated in dormant cancer cell-derived extracellular vesicles and particles (EVPs), which can be a predictive biomarker for cisplatin resistance." (PMID 36506554, 2022). "Nevertheless, in patients with established atherosclerotic coronary artery disease who are more prone to adverse cardiovascular events, the impact of HDL and ApoA1 on cancer‐related prognosis has been rarely addressed." (PMID 35796324, 2022). "In summary, our study demonstrated that ApoA1-lipsome, as a kind of biological drug-delivery carrier, is highly effective in transporting the anti-cancer drugs doxorubicin into MCF-7/ADR cells." (PMID 33652957, 2021). "Nonetheless, some investigators have increasingly turned their attention to the interaction between serum APOA-1 protein and cancer." (PMID 34790226, 2021). "Apolipoprotein A1 (APOA1) is a potential biomarker because of its variable concentration in different types of cancers." (PMID 34440141, 2021). "Some of the differently expressed proteins were significantly expressed in the groups EA/Ctrl, AIS/Ctrl, and AIS/EA, including myeloperoxidase and APOA1, which are involved in the development of cancer." (PMID 33194326, 2020).
cancer (continued). "Concerning many studies performed on APOA1 and its expression pattern changes in many cancers, we verified APOA1 downregulation by western blot as a control for our project." (PMID 31749922, 2019). "ApoA-1 has been reported to be a prognostic factor and is widely recognized and validated in several cancers, where it plays a role in anti-inflammatory, anti-apoptotic, and antioxidant activities." (PMID 30486825, 2018). "Recent studies have reported of an association between high serum apolipoprotein A1 (APOA1) levels and favorable prognosis in several malignancies, while the significance of apolipoprotein B (APOB) in cancer is less well-known." (PMID 28710487, 2017). "High APOA1 and APOB levels and low APOB/APOA1 ratio associated with improved cancer specific and overall survival." (PMID 28710487, 2017). "They include APOA1, VEGFC, YWHAZ, B2M, EIF2S1, CCR9 and many other genes that have been associated with the hallmarks of cancer." (PMID 25986937, 2015). "Despite the small overlap between differentially expressed protein sets in serum and tissue, APOA1 and Serotransferrin were significantly lower expressed in both serum and cancer tissue samples, suggesting a tissue-derived effect in serum." (PMID 25265318, 2014). "Recent studies demonstrated that administration of apoA1 mimetic peptides reduced the development of cancer in murine models." (PMID 23829168, 2013). "Nevertheless, in our longitudinal study we found that APOA1 rs670 predicted worse outcome after adjustment for ER/PR status, indicating alternative contributions from APOA1 rs670 in cancer progression." (PMID 23829168, 2013). "High-molecular-weight-kininogen, apolipoprotein A1, soluble vascular cell adhesion molecule-1, plasminogen activator inhibitor-1, vitamin-D binding protein and vitronectin were decreased in the cancer group." (PMID 19400944, 2009). "Most of the highly upregulated genes such as Cp, Apoa1, Ttr in liver metastatic lesions are known biomarkers for the detection of ovarian or other types of cancer." (PMID 18218118, 2008). "In our study, we identified dysregulation in the apolipoprotein A1/A2 ratio, a novel finding that has not been previously linked to cancer predisposition." (PMID 40137160, 2025). "In recent years, an increasing number of studies on ApoA1 in cancers have been conducted." (PMID 38212711, 2024). "Furthermore, it is unclear which protein component of the HDL, apolipoprotein A1, best describes the connection between the HDL and cancer risk." (PMID 38540127, 2024). "Reductions in apoA-1 plasma levels are related to the onset and progression of cancer and BC." (PMID 39195217, 2024). "Some molecules associated with γδ T cell activation such as the Butyrophilin (BTN)-family, UL16 Binding Protein (ULBP)-family, MHC Class I Polypeptide-Related Sequence A (MICA) and B (MICB), Annexin A2 (ANXA2), and Apolipoprotein A1 (APOA1 were lower in cancer organoids." (PMID 38090581, 2023). "One study suggested that HDL-C has anti-inflammatory and antioxidant properties, mediated mostly by APOA1, which could play a possible role in cancer mediation." (PMID 38067270, 2023). "There is a positive correlation between APOE and APOA1 across many of the analyzed cancers." (PMID 37304007, 2022). "Because cancer has recently become dominant as a cause of mortality in patients following PCI, serum ApoA1 level might be a useful prognostic tool to predict outcomes in patients who are going to undergo PCI." (PMID 35796324, 2022). "The findings indicate that serum apolipoprotein A1 level could be a useful prognostic indicator of cancer mortality in patients undergoing PCI." (PMID 35796324, 2022). "The level of apoA-1 is reduced in many cancers but increased in some." (PMID 36232415, 2022). "Additionally, some previous studies have indicated that abnormalities in serum lipids and lipoproteins, such as preoperative low levels of TC, HDL-C, ApoA1 or high TG levels, indicated poor prognosis in cancer patients." (PMID 34598703, 2021).
cancer (continued). "The results revealed that the expression of APOA-1 is varied with different types of cancer." (PMID 34790226, 2021). "It has been shown that the APOA1 concentration in blood is reduced in different types of cancer." (PMID 34440141, 2021). "Studies have also shown decreased ApoA1 levels in patients with malignant tumors." (PMID 33336932, 2021). "An important role of apolipoprotein A1 can also be supported by our last analysis, where apolipoprotein A1 was still associated with risk of cancer independent from HDL cholesterol, while the opposite was not applicable." (PMID 32998735, 2020). "Further, it is unclear whether it is HDL cholesterol per se or apolipoprotein A1, the major protein component of HDL, that best describe an association with risk of cancer." (PMID 32998735, 2020). "ApoA1 protein was strongly diminished in the cancer tissues, and this illustrates that cholesterol accumulation may, in part, result from impaired reverse cholesterol transport." (PMID 31905933, 2019). "The expression of APOA1 was reduced in some kinds of cancers while increased in others." (PMID 31573738, 2019). "Some studies have implied that ApoA-1 might play a significant role in tumorigenesis and cancer progression in HCC." (PMID 30486825, 2018). "Here we demonstrated that an ApoA1 mimetic peptide, employed at higher concentrations than the ones reported in previous studies, can affect Akt signaling and cancer cells sensitivity to platinum." (PMID 30745873, 2018). "However, controversial observations were also reported including up-regulation of Apolipoprotein A1 in a variety of malignant tumors of ovarian, liver, breast." (PMID 22970327, 2012). "It was shown that Apolipoprotein A1 concentration in blood is reduced in different types of cancer." (PMID 22970327, 2012). "Among these markers, decreased expression of ApoA1 was notable in cancer serum." (PMID 19400944, 2009). "Accordingly, HRs for any cancer were 1.06 for those with apolipoprotein A1 levels of 160–189 mg/dL, 1.18 for those with apolipoprotein A1 levels of 130–159 mg/dL, and 1.28 for those with apolipoprotein A1 levels < 130 mg/dL, in contrast to those with apolipoprotein A1 levels > 190 mg/dL." (PMID 38540127, 2024). "Additionally, it was proposed that, in addition to its antioxidant activity in cancer, APOA1 might have an inhibitory effect on tumor growth and progression and could have therapeutic effects in the treatment of cancer." (PMID 37375802, 2023). "In light of mechanistic insights into the association between reduced ApoA1 and the increased risk of cancer mortality, a significant inverse correlation between the extent of chronic systemic inflammation represented by hs‐CRP level and ApoA1 might be a possible explanation in our study." (PMID 35796324, 2022). "Furthermore, APOA1 has been correlated with survival in cancer patients." (PMID 35858961, 2022). "Moreover, previous observational studies indicated that patients with cancer or cancer history had increased risk of in‐hospital mortality following PCI33 and that elevated ratio of white blood cell count to ApoA1 at PCI was associated with all‐cause and cardiac mortalities." (PMID 35796324, 2022). "Therefore, we investigated the intracellular molecular mechanisms underlying anti-apoA-1 IgG-induced cytotoxicity on tumoral cells using various cancer cell lines, and compared them to non-tumoral cells." (PMID 33245719, 2020). "Thus, we cannot completely exclude that low HDL cholesterol and apolipoprotein A1 may just represent preclinical indicators of early cancer development." (PMID 32998735, 2020). "Therefore, we hypothesized that in combination with CRP, which reflects inflammation and poor survival of cancer patients, ApoA-1 may be a potent prognostic indicator in HCC patients." (PMID 30486825, 2018). "These suggest that these five cholesterol-related genes (APOA1, APOC3, ABCA1, NPC2, CD36) play an important role in cancer." (PMID 40302802, 2025).
cancer (continued). "This analysis identified several hub genes, including APOH, APOB, APOA1, and APOA2, which play significant roles in cancer progression." (PMID 39399493, 2024). "Emerging evidence suggests that the apolipoprotein A1/HDL axis, involved in lipid metabolism, is dysregulated in cancer." (PMID 38263244, 2024). "According to a recent publication, several proteins, including ABCA1, APOA1, APOE, apolipoprotein M (APOM), and SRB1, are involved in the influx and efflux of lipids in cancer cells." (PMID 37375802, 2023). "APOA1 and APOE are dysregulated in several tumors and interact with both the innate and adaptive immune system to sustain cancer cell proliferation." (PMID 36362243, 2022). "Several studies have showed that SERPINA1, APOA1, VCAN, and APOB mediated the development of cancer chemotherapy resistance." (PMID 34737677, 2021). "Another panel constituting of CA-125, ApoA1, TTR, and H418, was able to differentiate OC patients at early stage of disease from cancer-free healthy control samples with 74% sensitivity at 97% specificity." (PMID 31608277, 2019). "Other candidates, such as AP1B1, APOA1, YWHAH and YWHAZ, however, do not appear to be associated with docetaxel resistance in cancer." (PMID 34948097, 2021). "We identified ANGPT2 (logFC 3.9, FDR 2.00 × 10−4), APOA1(logFC −4.4, FDR 0.0067), FOS (logFC 1.4, FDR 0.0059) and VEGFA (z-score 2.228, overlap p-value 6.45 × 10−3) as the molecules of interest that have biomarker applications in various cancers." (PMID 35052372, 2021). "For DCIS tissues, compared with both DCIS cancer-adjacent and normal tissues, we detected four up-regulated (GAPDH, HSPA9, CCT4, and SCPEP1) and 48 down-regulated proteins (including KRT10, APOA1, ALDH1A1, and others) in DCIS tissues." (PMID 33194682, 2020). "The cancer-derived cells U251 and SUPT1, when treated with anti-apoA-1 IgGs for 48 and 72 h, presented the typical hallmarks of apoptosis: rounded and shrinked cells, detachment from the flask for U251, retraction of the nucleus with chromatin condensation, emission of apoptotic bodies." (PMID 33245719, 2020). "Anti-apoA-1 IgGs induced the activation of caspase 3 in Hela, another carcinoma derived-cell line but not in HEK293A or human primary macrophages." (PMID 33245719, 2020). "After antibody validation by Western blotting, it was verified that APOA1 (Apolipoprotein A-1) is down-regulated in two processes; normal toward polyp and subsequently cancer." (PMID 31749922, 2019). "The HDL-c and ApoA1 levels were shown to be inversely correlated with HIV-VL, and they could contribute to the documented increased prevalence of cancer in the HIV population." (PMID 27603338, 2016). "Note, an isoform of ApoA1 was already proposed as serum marker of HCC and based on IHC staining IL-1RA expression was confirmed in about 70% of mouse liver adenoma and carcinoma cases; however preneoplastic foci as well as normal hepatocytes surrounding the lesions were negative." (PMID 25872475, 2015). "HMWK, ApoA1, PAI-1, VDBP and vitronectin levels were significantly decreased in cancer patients." (PMID 19400944, 2009). "APOA1 plays a crucial part in lipid metabolism, however, by regulating cholesterol export and dampening COX-2 expression, APOA1 overexpression could curb the malignancy of cancer." (PMID 38074096, 2023). "Moreover, we propose an immunometabolic therapeutic approach targeting cholesterol efflux in TAMs through OV-targeted ApoA1 delivery, which has been proven effective and safe for GBM treatment and can be translated to other preclinical or clinical cancer therapies." (PMID 37474548, 2023). "Third, although data regarding mortality was precisely and rigorously corrected via electrical medical records and by periodic phone calls, data on cancer incidence is not available, indicating that the impacts of HDL and ApoA1 levels on cancer incidence were not evaluated in our study." (PMID 35796324, 2022).
cancer (continued). "However, the long‐term impact of ApoA1/HDL axis regarding cancer mortality in PCI patients has not been previously evaluated." (PMID 35796324, 2022). "In our study, ApoA1, and HDL subclasses were lower in participants meeting guidelines for cancer prevention which emphasis little to no alcohol compared to those who consumed more than one drink per day for women or two drinks per day for men." (PMID 34103643, 2021). "Furthermore, in several tissue microarray (TMA) cores, APOA1 and AGP were expressed strongly only in the stroma and inflammatory cells, but not in cancer cells, suggesting the host immune response to cancer." (PMID 32224886, 2020).